PROM1 (prominin 1)
Diseases named in the same sentence as PROM1 in open-access papers (continued):
Sharing a sentence is not in itself a finding about the gene and the disease.
serous ovarian cancer (8 papers, 2018 to 2025). "However, the expression of other CSC markers identified in serous ovarian cancer cells including PROM1 (CD133) and CD44 were not affected by 4-MU treatment in spheroids formed by the primary serous ovarian cancer cells." (PMID 31443261, 2019).
Blindness (7 papers, 2010 to 2024). Blindness is the condition of lacking visual perception defined as a profound reduction in visual perception. "In addition, prominin-1 deficient mice, which are viable and fertile, display blindness due to complete degeneration of mature photoreceptors." (PMID 20808829, 2010). "We found that PROM1-mediated blindness is light-independent and manifests at a very young age, prior to eye-opening, thus emphasizing PROM1's exclusive role in photoreceptors as a protein important for the normal development of outer segments." (PMID 38714794, 2024). "Intriguingly, prominin-1 knockout mice do not suffer from gross abnormalities, but do show signs of blindness, which suggest that SV8 has a specific function in this tissue." (PMID 20808829, 2010). "Likewise, no major phenotype, other than blindness, has been detected in patients carrying dominant or recessive mutations in the PROM1 gene, suggesting that CD133 is dispensable for general stem cell properties under physiological conditions." (PMID 38532366, 2024).
end stage renal disease (7 papers, 2014 to 2025). "In contrast, the absence of Prominin-1 (CD133) was indicated as a biomarker in the end-stage renal disease." (PMID 35586196, 2022).
Obesity (6 papers, 2013 to 2026). Accumulation of substantial excess body fat. "Studies have pointed to the potential involvement of Prom1 in cellular metabolism in rat myotubes and mouse pancreatic islets with contrasting findings, and an increase in Prom1 expression in young mice with induced obesity has been reported." (PMID 25954606, 2015).
virus infection (6 papers, 2011 to 2023). "Neither Prominin-1 (CD133) nor vesicle-associated membrane protein-associated protein A (VAPA) has been found to have a role in viral infection, including SARS-CoV-2 infection." (PMID 36152751, 2022). "To test this theory, we crossed the Prom1 KO mouse with a conditional Shp2flox/flox mouse line, and deleted Shp2 in hepatocytes by AAV-Cre virus infection." (PMID 37846866, 2023).
injury (5 papers, 2014 to 2025). Damage inflicted on the body as the direct or indirect result of an external force, with or without disruption of structural continuity. "Collectively, these data indicate that the presence of Prom1‐expressing HPCs positively correlates with biliary fibrogenesis in cholestatic liver injury." (PMID 32686913, 2020).
kidney cancer (5 papers, 2013 to 2022). Primary or metastatic malignant neoplasm involving the kidney. "In kidney cancers, we observed a positive correlation between PROM1 expression and high rates of survival." (PMID 31164716, 2020). "Meanwhile, both PROM1 and PROM2 are potential targets for skin and kidney cancers." (PMID 31164716, 2020).
myopia (5 papers, 2009 to 2025). "The co-occurrence of myopia and CORD, as seen in our patients, aligns with previous cases involving PROM1 mutations and X-linked high myopia." (PMID 41293231, 2025). "Although it is plausible that PROM1 is implicated in the pathogenicity of myopia, a more likely explanation is that the myopia is induced by sensory deprivation owing to blurring of vision in patients with PROM1 sequence variations." (PMID 31199449, 2019). "In such a case the neighboring gene fibroblast growth factor binding protein-1 (FGFBP1; OMIM 607737), located approximately 30 kb from PROM1, is a potential candidate gene for the observed myopia." (PMID 19718270, 2009). "It is plausible that the PROM1 mutation may have contributed for both CORD and high myopia in this family." (PMID 19718270, 2009). "However absence of myopia in the other PROM1-related phenotypes and lack of PROM1 expression in the sclera argues against PROM1 involvement in the pathogenesis of the myopia." (PMID 19718270, 2009).
age-related macular degeneration (4 papers, 2024 to 2025). Age-related loss of vision in the central portion of the retina (macula), secondary to retinal degeneration. "Recent studies on animal models have confirmed its role in RPE homeostasis and retinal health, providing insights on considering PROM1 a target for potential future therapeutic strategies, not only for IRDs, but also for age-related macular degeneration (AMD)." (PMID 41300751, 2025).
endometriosis (4 papers, 2013 to 2025). The growth of functional endometrial tissue in anatomic sites outside the uterine body. "In this study, we investigated the expression and localisation of the proteins, osteopontin (OPN) and prominin-1 (CD133), as well as the plasma OPN levels in the endometrium of patients with endometriosis." (PMID 23545719, 2013).
Leber congenital amaurosis (4 papers, 2015 to 2024). Leber congenital amaurosis (LCA) is a retinal dystrophy defined by blindness and responses to electrophysiological stimulation (Ganzfeld electroretinogram (ERG)) below threshold, associated with severe visual impairment within the first year of life. "For example, mutations in ABCA4, CRX, CERKL, PROM1, SEMA4A, GUCY2D can cause either CCRD, but also RP or Leber congenital amaurosis (LCA)." (PMID 26103963, 2015).
pulmonary fibrosis (4 papers, 2011 to 2024). Chronic progressive interstitial lung disorder characterized by the replacement of the lung tissue by connective tissue, leading to progressive dyspnea, respiratory failure, or right heart failure. "Herein, we addressed the contribution of lung microenvironment and prominin-1+ bone marrow-derived epithelial progenitor cells in the mouse model of bleomycin-induced experimental pulmonary fibrosis." (PMID 21943210, 2011). "Administration of prominin-1+ cells 2 hours after bleomycin instillation protects from pulmonary fibrosis, and some of progenitors differentiate into alveolar type II epithelial cells." (PMID 21943210, 2011). "In this study we demonstrated that bone marrow-derived cells, and in particular, prominin-1+ progenitors represent one of the cellular sources for myofibroblasts in bleomycin-induced experimental pulmonary fibrosis." (PMID 21943210, 2011). "Thus, it will be interesting to expand our understanding of the PROM1-SMAD7 interaction to explain the antifibrogenic effect of PROM1 in lung fibrosis." (PMID 36038590, 2022). "Increased bone marrow-derived prominin-1+ progenitors within the inflamed and fibrotic lungs suggest an active contribution of this cell subpopulation to the development of bleomycin-induced experimental pulmonary fibrosis." (PMID 21943210, 2011). "Furthermore, our results showed that administration of prominin-1+ progenitors only 2 hours after bleomycin instillation prevents pulmonary fibrosis development." (PMID 21943210, 2011). "Indeed, the antifibrogenic roles of PROM1 have also been found in lung fibrosis." (PMID 36038590, 2022).
alcoholic hepatitis (3 papers, 2020 to 2025). Acute hepatitis resulting from ingestion of alcohol. "Cg21230392 is mapped to the PROM1 gene, which is a relevant progenitor marker in human alcoholic hepatitis and showed increased expression in mice fed with alcohol." (PMID 38249614, 2023). "PROM1-positive (PROM1+) cells also accumulate in mouse liver injury models and livers of alcoholic hepatitis (AH) patients in the pattern commonly characterized as ductular reaction progenitors (DRPs)." (PMID 33173221, 2020).
Alzheimer disease (3 papers, 2020 to 2024). A progressive, neurodegenerative disease characterized by loss of function and death of nerve cells in several areas of the brain leading to loss of cognitive function such as memory and language. "The Alzheimer disease-amyloid secretase pathway was the most significant pathway associated with the PROM1-correlated gene, whereas the EGF receptor signaling pathway was the key player in the PROM2-correlated gene cluster." (PMID 31164716, 2020).
Atrophy (3 papers, 2024 to 2025). Any weakening or degeneration, especially through lack of use. "This study uncovered evidence of subretinal drusenoid-like deposits, thinning of RPE, and RPE atrophy in Prom1-null frogs, suggesting that the loss of Prom1 primarily impairs RPE function." (PMID 39513868, 2024).
bone metastasis (3 papers, 2010 to 2022). Transfer of a neoplasm from its primary site to bones. "PROM1 was an important biomarker associated with BRCA bone metastasis and affected the prognosis of metastatic BRCA patients." (PMID 36193308, 2022). "Quantitative analysis just revealed the significant expression difference of PROM1 between BRCA samples with or without bone metastasis." (PMID 36193308, 2022). "This study identified 74 DEGs between BRCA samples with or without bone metastasis, and 5 important DEGs were finally filtered, namely, MMP9, ITGB3, BMP2, CCL2, and PROM1." (PMID 36193308, 2022). "However, both PROM1 and CCL2 exerted no significant impacts on the survival of single BRCA bone metastasis patients, which might be due to the insufficient sample size." (PMID 36193308, 2022).
COVID-19 (3 papers, 2021 to 2023). A disease caused by infection with severe acute respiratory syndrome coronavirus 2. "This novel technology has been used successfully in several organs—for example, to study Prominin 1+ liver progenitors, Dach1–downregulated lymphoid progenitors and KTR5+ lung progenitors in COVID-19 patients." (PMID 33401654, 2021).
cutaneous melanoma (3 papers, 2008 to 2024). A primary melanoma arising from atypical melanocytes in the skin. "Expression of the surface protein CD133 (also known as AC133 and prominin-1) is one criterion which has been used in the identification of putative cancer stem cells from solid tumors (brain:, lung:, skin melanoma:, prostate:, kidney:, colon:, liver:)." (PMID 18261235, 2008).
intestinal tumors (3 papers, 2014 to 2025). "Also, Prom1 knockout mice are more susceptible to intestinal tumor formation." (PMID 25452936, 2014). "Characterization of Prom1 holds significant promise for eventual treatment of intestinal tumors and many gastrointestinal diseases such as Crohn’s Disease." (PMID 25452936, 2014). "Taken together, our results suggest that Prom1-/- induces inflammation and increases proliferative potential in the intestinal crypts enhanced intestinal tumor genesis." (PMID 25452936, 2014). "We evaluated the role of Prom1 in intestinal regeneration in inflammatory bowel disease (IBD), determined the function of Prom1, and characterized the effect of a lack of Prom1 on intestinal tumor formation in animal models." (PMID 25452936, 2014).
Salivary Gland Tumors (3 papers, 2011 to 2024). "Collectively, our findings bring new insights into the biochemistry and trafficking of prominin-1 as well as its immunohistochemical profile in certain types of salivary gland tumors and inflammatory diseases." (PMID 24911657, 2014).
seminoma (3 papers, 2015 to 2022). A radiosensitive malignant germ cell tumor found in the testis (especially undescended), and extragonadal sites (anterior mediastinum and pineal gland). "From them, EC-, pluripotency- and reprogramming-associated genes REX1 (ZFP42), DND1, JARID2 and PRDM14 were hypomethylated and upregulated, while seminoma-related genes PRDM1, PROM1 and IGF1 became hypermethylated and were downregulated." (PMID 26226633, 2015).
Stargardt disease type 4 (3 papers, 2017 to 2025). "Likewise, for PROM1, associated with Stargardt disease type 4 and dominant macular dystrophy, IP and VE seems to be a common trait linked to mutations in this gene." (PMID 29053642, 2017).
bone tumor (2 papers, 2010 to 2019). "Significantly, this PROM1-high, EWS-ERG+ bone tumor was highly drug resistant and the level of PROM1 (data not shown) and frequency of CD133+ cells increased further following induction chemotherapy suggesting that the CD133+ cells were relatively more chemo-resistant than their CD133- counterparts." (PMID 20346143, 2010).
cervical squamous cell carcinoma (2 papers, 2019 to 2024). A squamous cell carcinoma arising from the cervical epithelium. "However, there are challenges in identifying specific markers for cervical squamous cell carcinoma (CCSC), including ABCG2, MSI1, PROM1 (CD133), ITGA6 (CD49f), KRT17 (CK17), SOX2, and Pou5f1 (OCT4)." (PMID 38651153, 2024).
ciliopathies (2 papers, 2023 to 2024). "CFAP45 and PROM1 are found in both atypical and secondary ciliopathies, whereas TTC26, SCLT1, DNAJB11, DYNC2LI1, ALMS1, IFT80 and IFT74 are shared between primary and atypical ciliopathies." (PMID 37542408, 2023).
ovarian clear cell cancer (2 papers, 2017 to 2023). An invasive malignant neoplasm that arises from the ovary and is characterized by a predominance of clear and hobnail malignant epithelial cells. "In support of this possibility, a recent study has shown that CD133 (prominin-1), a marker of stem cell and CSCs, interacted with plakoglobin in ovarian clear cell carcinoma CSCs." (PMID 28416759, 2017).
uterine cancer (2 papers, 2020 to 2022). Primary or metastatic malignant neoplasm involving the uterine corpus and/or the cervix. "We also observed that PROM1 mutations primarily occurred in uterine cancer and spanned the prominin domain, with a hotspot in N566Ifs*29/Kfs*2." (PMID 31164716, 2020).
biliary atresia (1 paper, 2020). A rare, biliary tract disease characterized by progressive obliterative cholangiopathy of the intra- and extrahepatic bile ducts, occurring in the embryonic/ perinatal period, leading to severe and persistent neonatal jaundice and acholic stool. "Previously, we demonstrated that in biliary atresia, Prom1(+) HPCs are present within developing fibrosis and that null mutation of Prom1 significantly abrogates fibrogenesis." (PMID 32686913, 2020).
Cholestatic liver disease (1 paper, 2020). "Further studies are necessary to more definitively define Prom1(+) HPCs influence on portal fibroblasts in the fibrogenesis of cholestatic liver disease." (PMID 32686913, 2020).
choroid plexus carcinoma (1 paper, 2013). A malignant neoplasm arising from the choroid plexus. "The neuroepithelium-derived cuboidal choroid plexus epithelium, however, lacks prominin-1 consistent with a recent case report showing that choroid plexus carcinoma is negative for prominin-1." (PMID 23723983, 2013).
choroidal neovascularization (1 paper, 2025). An eye disorder described by the growth of new blood vessels that originate from the choroid through a break in the Bruch membrane into the sub–retinal pigment epithelium (sub-RPE) or subretinal space. "CRB1 was statistically linked to epiretinal membrane (ERM) (p = 0.003), EYS with cataract (p = 0.001), PROM1 with choroidal neovascularization (CNV) (p = 0.0026), and USH2A with macular hole (p = 0.01)." (PMID 40725401, 2025).
dysplasia (1 paper, 2014). A usually neoplastic transformation of the cell, associated with altered architectural tissue patterns. "Knockout of Prom1 results in significantly greater intestinal inflammation, abnormal crypt proliferation, and dysplasia upon AOM/DSS administration." (PMID 25452936, 2014).
Gliosis (1 paper, 2021). Gliosis is the focal proliferation of glial cells in the central nervous system. "Gliosis, a phenotype we identified in Prom1-KO mice, is a common feature of RP." (PMID 34664634, 2021).
hyperplastic polyp (1 paper, 2021). A polyp found mainly in the stomach and colon. "In hyperplastic polyps (group 1), there was a significant decrease in the expression of PROM1 (p: 0.01), POU5F1 (p: 0.02), LGR5 (p: 0.01) and REX1 (p: 0.01) genes compared to the control group." (PMID 34452555, 2021).
hypersensitivity pneumonitis (1 paper, 2007). Hypersensitivity pneumonitis (HP) is a pulmonary disease with symptoms of dyspnea and cough resulting from the inhalation of an antigen to which the subject has been previously sensitized. "The cellular source of A2BAR and prominin-1, two highly upregulated genes in “rapid” progressor patients, was determined by immunohistochemistry in “rapid” and “slow” progressor IPF lungs as well as in hypersensitivity pneumonitis and normal control lungs." (PMID 17534432, 2007).
Insulin resistance (1 paper, 2021). Increased resistance towards insulin, that is, diminished effectiveness of insulin in reducing blood glucose levels. "In addition to the photoreceptor-related genes, the expression of genes related to insulin resistance and metabolism was also downregulated in the Prom1-KO retina at P21." (PMID 34664634, 2021).
leukocytosis (1 paper, 2014). "Peripheral complete blood counts revealed significant leukocytosis, neutrophilia, and monocytosis in Prom1 knockout mice compared with the wild-type mice." (PMID 25452936, 2014).
macular holes (1 paper, 2025). A hole in the macula of the retina. "When comparing the prevalence of specific genes and comorbidities, we found the following associations in AR RP: CRB1 was statistically associated with ERM (p = 0.003), EYS with cataract (p = 0.001), PROM1 with CNV (p = 0.0026), and USH2A with macular hole (p = 0.01)." (PMID 40725401, 2025).
male infertility (1 paper, 2024). The inability of the male to effect fertilization of an ovum after a specified period of unprotected intercourse. "This indicates potential functional redundancy of CD133 in specific tissues, despite a recent study reporting male infertility after deletion of the Prom1 gene in a particular mouse background." (PMID 38532366, 2024).
ovarian dysfunction (1 paper, 2025). The inability of the ovaries to function. "Ultimately, 2 overlapping genes, including WFS1 and DRD5, for the neurodevelopment and 4 ovarian dysfunction-related genes, including WFS1, CC2D2A, PROM1 and QDPR, were identified." (PMID 41185014, 2025). "Through analysis of Genecards and OMIM databases, we identified two neurodevelopmental genes DRD5 and WFS1, and four ovarian dysfunction-related genes WFS1, CC2D2A, PROM1, and QDPR, suggesting their roles in the patient’s manifestations." (PMID 41185014, 2025). "Within the deleted region, four candidate genes (WFS1, CC2D2A, PROM1, and QDPR) warrant detailed discussion regarding their potential roles in ovarian dysfunction." (PMID 41185014, 2025).
paracoccidioidomycosis (1 paper, 2023). A systemic fungal infection caused by Paracoccidioides brasiliensis that is most often seen in immunocompromised patients. "Therefore, our research indicates that the CLEC7A and PROM1 genes are important for the cytokine response induced by P. brasiliensis and may influence the Paracoccidioidomycosis disease outcome." (PMID 37108883, 2023).
presbycusis (1 paper, 2018). Bilateral hearing loss caused by progressive degeneration of cochlear structures and central auditory pathways, typically associated with the aging process. "Therefore, the development of an efficient method to analyze the differentiation of neural stem cells expressing prominin-1 into GABAergic neurons may be a new strategy to cure presbycusis using regenerative medicine." (PMID 28795331, 2018).
retinal (1 paper, 2024). "The intricate relationship between Prom1 and microglia underscores the complexity and importance of understanding Prom1-related retinal pathologies." (PMID 39513868, 2024).
Salivary Gland Diseases (1 paper, 2014). "Differential immunoreactivity of prominin-1 and other cancer markers in distinct salivary gland diseases." (PMID 24911657, 2014).
salivary gland lesion (1 paper, 2014). "The expression of murine and human prominin-1 in major salivary glands and the presence of prominin-1–containing membrane vesicles in human saliva have drawn our attention to its expression in salivary gland lesions." (PMID 24911657, 2014).